ACER2 (alkaline ceramidase 2)
Description:
Golgi ceramidase that catalyzes the hydrolysis of ceramides into sphingoid bases like sphingosine and free fatty acids at alkaline pH. Ceramides, sphingosine, and its phosphorylated form sphingosine-1-phosphate are bioactive lipids that mediate cellular signaling pathways regulating several biological processes including cell proliferation, apoptosis and differentiation. Has a better catalytic efficiency towards unsaturated long-chain ceramides, including C18:1-, C20:1- and C24:1-ceramides. Saturated long-chain ceramides and unsaturated very long-chain ceramides are also good substrates, whereas saturated very long-chain ceramides and short-chain ceramides are poor substrates. Also hydrolyzes dihydroceramides to produce dihydrosphingosine. It is the ceramidase that controls the levels of circulating sphingosine-1-phosphate and dihydrosphingosine-1-phosphate in plasma through their production by hematopoietic cells (By similarity). Regulates cell proliferation, autophagy and apoptosis by the production of sphingosine and sphingosine-1-phosphate. Through the production of sphingosine, may also regulate the function of the Golgi complex and regulate the glycosylation of proteins.
Synonyms: ASAH3L; FLJ41587; ALKCDase2
Tractability: Antibody: UniProt predicts a signal peptide or a membrane-spanning region. PROTAC: a small molecule that binds it is known.
Target class: Enzyme; Hydrolase
Gene: Protein-coding gene on chromosome 9 (19,409,009 to 19,452,505, forward strand). Ensembl gene ENSG00000177076.
Subcellular location: Golgi apparatus membrane
Pathways (Reactome):
Metabolism: Sphingolipid catabolism
Gene Ontology:
Molecular function: N-acylsphingosine amidohydrolase activity
Biological process: cellular response to xenobiotic stimulus; ceramide catabolic process; DNA damage response; negative regulation of cell adhesion mediated by integrin; negative regulation of cell-matrix adhesion; positive regulation of cell population proliferation; regulation of apoptotic process; regulation of autophagy; regulation of glycoprotein biosynthetic process; response to retinoic acid; sphingosine biosynthetic process; sphingolipid catabolic process; ceramide metabolic process; sphingolipid metabolic process
Cellular component: Golgi apparatus; Golgi membrane; membrane
Genetic constraint (gnomAD): Loss-of-function variants: 24 observed, 29.23 expected, observed/expected ratio (o/e) 0.82, 90% interval 0.59 to 1.15. The upper end of that interval is the gene's LOEUF score, 1.15, which puts it in group 5 of 6, group 1 being the genes least tolerant of losing a copy. Missense variants: 352 observed, 332.08 expected, observed/expected ratio (o/e) 1.06, 90% interval 0.97 to 1.16. Synonymous variants: 138 observed, 130.26 expected, observed/expected ratio (o/e) 1.06, 90% interval 0.92 to 1.22.
Homologues: Orthologues: chimpanzee ACER2 (100% identical), macaque ACER2 (98% identical), rabbit ACER2 (96% identical), guinea pig ACER2 (96% identical), pig ACER2 (94% identical), mouse Acer2 (93% identical), tropical clawed frog acer2 (86% identical), dog ACER2 (84% identical), zebrafish acer2 (83% identical), rat Acer2 (69% identical), Drosophila melanogaster bwa (48% identical), Caenorhabditis elegans W02F12.2 (28% identical). Paralogues in human: ACER1 (37% identical), ACER3 (26% identical).
Diseases named in the same sentence as ACER2 in open-access papers:
ACER2 is named in the same sentence as 34 diseases in open-access papers, as found by Europe PMC text mining. Sharing a sentence is not in itself a finding about the gene and the disease. The quoted sentences say what the papers report.
hepatocellular carcinoma (6 papers, 2022 to 2025). A malignant tumor that arises from hepatocytes. "Dysregulation of ACER2 has been implicated in various gastrointestinal cancers, including colorectal cancer, gastric cancer, and hepatocellular carcinoma." (PMID 39650647, 2024). "ACER2 has been implicated in hepatocellular carcinoma (HCC) as well." (PMID 39650647, 2024). "ACER2, one of the key enzymes that regulates ceramide hydrolysis, is overexpressed in hepatocellular carcinoma tissues and cell lines, and ACER2 knockdown resulted in decreased tumor cell growth and migration." (PMID 36594091, 2023). "Meanwhile, ACER2 was revealed to promote the growth, invasion, and migration of hepatocellular carcinoma cells." (PMID 36936425, 2023). "ACER2 was reported to be overexpressed in hepatocellular carcinoma (HCC) tissue and to induce growth, invasion, and migration in HCC cell lines via sphingomyelin phosphodiesterase acid-like 3B (SMPDL3B)." (PMID 35565311, 2022). "In addition, NC regulates colon cancer initiation and development, ACER3 promotes growth of hepatocellular carcinoma cells and supports AML survival, and ACER2 is involved in hepatocellular carcinoma and estrogen receptor-positive breast tumorigenesis." (PMID 38369184, 2024).
atherosclerosis (4 papers, 2021 to 2023). A disease characterized by the build-up of fatty material and calcium deposition in the arterial wall resulting in partial or complete occlusion of the arterial lumen. "Overexpression of ACER2 has been shown to rescue HIF-2α-deficiency-induced exacerbation of atherosclerosis." (PMID 37308908, 2023). "In addition, a study found that the adipose overexpression of Acer2 rescued adipocyte HIF‐2α‐deficiency‐induced exacerbation of atherosclerosis." (PMID 38020719, 2023). "Research in our laboratory reported that cold exposure upregulated adipocyte hypoxia-inducible factor 2α (HIF-2α), targeting the Acer2 gene, which encodes alkaline ceramidase 2, triggering ceramide catabolism and mediating cold-induced thermogenesis, thereby alleviating atherosclerosis." (PMID 33346905, 2021). "ACER2 expression is in-part regulated by the hypoxia-inducible factor 2α, an atherosclerosis suppressor and known ischemic stroke marker." (PMID 33661917, 2021).
breast carcinoma (4 papers, 2020 to 2022). "TIM can regulate sphingolipid metabolism and promote tumor cell growth through Sp1/ACER2/S1P axis in breast cancer." (PMID 34490127, 2021). "Another study revealed that TIM regulated the sphingolipid metabolism through Sp1/ACER2/S1P axis, promoting the tumor cell growth of breast cancer." (PMID 34490127, 2021). "Taken together, these data indicated that the promotive effect of TIM on proliferation and mitochondrial respiration were primarily mediated by ACER2 in breast cancer cells." (PMID 33093451, 2020). "As expected, overexpressing ACER2 in TIM-knockdown breast cancer cell rescued the cell growth and the ability of colony formation." (PMID 33093451, 2020). "Collectively, these findings demonstrated that TIM facilitated S1P biosynthesis in breast cancer cells by modulating ACER2 expression." (PMID 33093451, 2020). "In estrogen receptor-positive breast cancer, the most prevalent type of breast cancer, SP1 interacts with the circadian gene TIMELESS (TIM) to increase alkaline ceramidase 2 (ACER2) and enhance mitochondrial respiration." (PMID 36077352, 2022). "TIMELESS promoted breast cancer progression by activating MYC and regulated cancer cell progression via the Sp1/ACER2/S1P axis." (PMID 35715407, 2022). "High expression of TIM in breast cancer predicts poor prognosis and TIM regulates tumor cell growth and sphingolipid metabolism through Sp1/ACER2/S1P axis." (PMID 33093451, 2020). "We next investigated whether overexpression of ACER2 could abolish the inhibition of TIM knockdown on the proliferation and the mitochondrial respiration of breast cancer cells." (PMID 33093451, 2020).
diffuse large B-cell lymphoma (3 papers, 2024 to 2025). "YTHDF2 also promotes the progression of diffuse large B-cell lymphoma by regulating alkaline ceramidase 2-mediated ceramide metabolism in an m6A-dependent manner." (PMID 39593172, 2024). "Similarly, YTHDF2 promotes diffuse large B-cell lymphoma (DLBCL) progression by modulating ACER2-mediated ceramide metabolism in an m6A-dependent manner." (PMID 40332203, 2025). "Enhanced ACER2 expression hydrolyzed ceramides, disrupting the balance between Cer and S1P, activating the ERK and PI3K/AKT pathways, and leading to diffuse large B-cell lymphoma (DLBCL) tumorigenesis." (PMID 39650647, 2024).
colon cancer (2 papers, 2019 to 2024). "Elevated ACER2 mRNA expression has been observed in human cancer tissues, including liver and colon cancers, compared to healthy samples." (PMID 39650647, 2024).
diabetes (2 papers, 2024 to 2025). "Recent investigations have identified a unique retinal EC population in diabetes alongside a negative feedback regulatory pathway that attenuates endothelial dysfunction by upregulating alkaline ceramidase 2 (ACER2) expression to decrease ceramide content." (PMID 39723239, 2024).
gastric cancer (2 papers, 2023 to 2024). A primary or metastatic malignant neoplasm involving the stomach. "Whereas, a current investigation revealed a lower ACER2 elevated gastric cancer cell proliferation and migration ability, and thus inhibited apoptosis." (PMID 36936425, 2023). "miR-196a-5p is associated with the progression from chronic atrophic gastritis to gastric cancer (GC) and promotes the malignant behavior of GC cells by directly targeting the 3’UTR of ACER2 mRNA, reducing its expression." (PMID 39650647, 2024).
Hernia (2 papers, 2020 to 2021). "The KCNMA1 gene (Potassium Calcium—Activated Channel Subfamily M α 1), which was upregulated in animals affected with hernia, and ACER2 (downregulated) were enriched in the apoptosis BP." (PMID 33513662, 2021). "The microtubule associated protein 1 light chain 3 γ (MAP1LC3C), vitrin (VIT), aggrecan (ACAN), alkaline ceramidase 2 (ACER2), potassium calcium-activated channel subfamily M α 1 (KCNMA1) and synaptopodin 2 (SYNPO2) genes are highlighted as candidates to trigger both types of hernia." (PMID 33513662, 2021).
Obesity (2 papers, 2023 to 2024). Accumulation of substantial excess body fat. "Genetic loss of HIF2α in mice reversed UMP‐mediated Acer2 activation and obesity alleviation, and we conclude from our findings that a HIF2α‐ACER2‐ceramide axis underlies the mechanism through which UMP supplementation can alleviate obesity features and restore metabolic traits." (PMID 38460165, 2024). "UMP replenishment can alleviate obesity by recovering ceramide chaos in a HIF2α‐ACER2 signaling dependent mode." (PMID 38460165, 2024). "Taken together, we find that UMP levels can influence obesity through the restoration of metabolic homeostasis via a HIF2α‐ACER2‐ceramide signaling axis that is relevant for metabolic homeostasis and obesity." (PMID 38460165, 2024). "Using adipose tissue Hif2α‐specific knockout mice, the study further demonstrates that the presence of UMP can alleviate obesity through a HIF2α‐ACER2‐ceramide pathway, which can be a new signaling axis for obesity improvement." (PMID 38460165, 2024). "Taken together, our data suggests that UMP supplementation restores ceramide metabolism and improves obesity through a molecular pathway involving an HIF2α‐ACER2 signaling axis." (PMID 38460165, 2024). "Furthermore, they demonstrate that the presence of UMP can alleviate obesity through a HIF2α‐ACER2‐ceramide pathway, which can be a new signaling axis for obesity improvement." (PMID 38460165, 2024). "We speculate that targeting UMP and the HIF2α‐ACER2‐ceramide axis is relevant to the prevention and treatment of obesity." (PMID 38460165, 2024). "Additionally, whether the Acer2‐mediated signal is also responsible for the anti‐obesity effect of L. reuteri in mice needs to be further explored." (PMID 38020719, 2023). "However, only the inhibition of HIF2α and its target gene Acer2 was achieved by UMP supplementation in mice, and this was accompanied by the alleviation of ceramide accumulation and obesity features." (PMID 38460165, 2024). "Also, we conduct experiments with genetically modified Hif2α△adipo mice to show that Hif2α and its downstream target gene, alkaline ceramidase 2 (Acer2), are activated by UMP and this triggers ceramide decomposition, leading to reductions in ceramide levels and obesity traits." (PMID 38460165, 2024).
B-cell acute lymphoblastic leukemia (1 paper, 2021). A neoplasm of lymphoblasts committed to the B-cell lineage, typically composed of small to medium-sized blast cells. "ACER3 coregulates cell proliferation and survival with ACER2 and plays an important role in leukemia development; while TCL6 is associated with clinical outcomes of B-cell acute lymphoblastic leukemia patients; TFDP2 plays core roles in apoptosis and cell proliferation." (PMID 34722498, 2021).
bladder cancer (1 paper, 2023). "ACER2 was significantly higher expressed in bladder cancer cell lines in comparison to bladder epithelial cell lines." (PMID 36936425, 2023).
breast tumor (1 paper, 2025). "Further comparison of ACER2 expression across various types of breast tumor types revealed lower expression levels in TNBC tumors compared to other subtypes." (PMID 41345520, 2025). "In addition, we found that the expression of the ACER2 gene is significantly downregulated in TNBC and HER2-positive breast tumor samples compared to normal samples." (PMID 41345520, 2025).
chronic obstructive pulmonary disease (1 paper, 2020). A chronic and progressive lung disorder characterized by the loss of elasticity of the bronchial tree and the air sacs, destruction of the air sacs wall, thickening of the bronchial wall, and mucous accumulation in the bronchial tree. "However, an overexpression of ACER2 has been associated with chronic obstructive pulmonary disease (COPD)." (PMID 32498325, 2020).
Cognitive impairment (1 paper, 2024). Abnormal cognition is characterized by deficits in thinking, reasoning, or remembering. "During chronic hypoxia, hyperphosphorylation of α-syn occurs, enhancing ceramide catabolism through HIF-2α and HIF-2α-dependent transcriptional activation of Acer2, which is implicated in α-syn pathology and cognitive impairment in mice." (PMID 39408813, 2024). "Additionally, the data suggest that HIF-2α promotes α-syn hyperphosphorylation at the serine 129 site (pS129-αSyn) and abnormal aggregation of pS129-αSyn by upregulating alkaline ceramidase 2 (Acer2), which leads to cognitive impairment in mice." (PMID 39408813, 2024).
COVID-19 (1 paper, 2020). A disease caused by infection with severe acute respiratory syndrome coronavirus 2. "It has been speculated that younger children suffer less severe acute COVID-19 due to reduced ACEr2 expression, although recent studies have shown younger children have lower ACEr2 expression but not viral load." (PMID 33330288, 2020).
glioma (1 paper, 2022). A benign or malignant brain and spinal cord tumor that arises from glial cells (astrocytes, oligodendrocytes, ependymal cells). "In contrast, there was no signficant correlation of elevated expression of other ceremidases (ASAH2, ACER2, ACER3) with poor glioma patient outcomes." (PMID 35741006, 2022).
head and neck cancer (1 paper, 2016). A primary or metastatic malignant neoplasm affecting the head and neck. "We previously demonstrated that ACER2 can also be upregulated by the retinoid 4-HPR in SCC14 head and neck cancer cells and that its upregulation mediates the 4-HPR-induced generation of dihydrosphingosine (DHS), which in turns induces the death of these cells." (PMID 26943039, 2016).
Hypertension (1 paper, 2011). The presence of chronic increased pressure in the systemic arterial system. "In a case-control design using these definitions of hypertension the maximal single-gene heritabilities did not exceed 0.0034 and were all represented by the same three SNPs in ACER1, ACER2, and CERKa." (PMID 21569466, 2011).
lung carcinoma (1 paper, 2024). "This includes genes involved in cancer progression such as Kif26a, Acer2, Serpine1, Nr1d2, Efnb2 as well as Chst11, which have all previously been shown to be deregulated in various forms of cancer, including lung cancer." (PMID 39273313, 2024).
type 2 diabetes (1 paper, 2024). "Research conducted by the Guo group demonstrated that miR-125b-5p, isolated from ADSC-Exos and identified via differential gene expression analysis, likely plays a pivotal role in targeting ACER2 for reparative functions in ischemic muscles associated with type 2 diabetes." (PMID 39450105, 2024).